MMP14 (matrix metallopeptidase 14)
Diseases named in the same sentence as MMP14 in open-access papers (continued):
Sharing a sentence is not in itself a finding about the gene and the disease.
leukemia (4 papers, 2010 to 2025). A malignant (clonal) hematologic disorder, involving hematopoietic stem cells and characterized by the presence of primitive or atypical myeloid or lymphoid cells in the bone marrow and the blood. "Building upon these insights, we selected several molecules closely associated with leukemia progression and examined the impact of MMP14 knockdown on the gene expression of cytokines in MSCs." (PMID 40121502, 2025). "It is strongly linked to the progression of hematological malignancies.Our data show that MSC-derived MMP14 activates the JAK-STAT pathway in leukemia cells by regulating PGE2 secretion." (PMID 40121502, 2025). "Flow cytometry analysis of apoptosis revealed that knockdown of MMP14 increased the apoptosis rate in primary leukemia cells." (PMID 40121502, 2025). "The proportion of bone marrow and splenic leukemia cells in mice treated with the combination of MMP14 inhibitor and cytarabine was significantly lower than in the control and single-agent groups." (PMID 40121502, 2025). "To this end, we established the MLL-AF9 leukemia model by intrafemoral injection of MMP14 knockdown or control MSCs, followed by tail vein injection of MLL-AF9 cells." (PMID 40121502, 2025). "To further elucidate the role of MSC-derived MMP14 in primary leukemia cells, we obtained cells from two distinct patients and co-cultured them with MMP14 knockdown and control MSCs." (PMID 40121502, 2025). "Furthermore, bone marrow smears demonstrated a significant reduction in leukemia cells in the MMP14 inhibitor combined with cytarabine group, and infiltration of splenic leukemia cells was diminished as evidenced by histological H&E staining." (PMID 40121502, 2025). "Although there is substantial evidence that MMP14 is aberrantly expressed in leukemia, the role of MSC-derived MMP14 in AML and its impact on the microenvironment remain unclear." (PMID 40121502, 2025). "In conclusion, our findings suggest that inhibition of MMP14 suppresses AML patient blasts, underscoring its potential as a therapeutic target in leukemia." (PMID 40121502, 2025). "Mechanistic studies revealed that MMP14-mediated alterations in the AML stromal microenvironment are driven by PGE2 secretion and activation of the JAK-STAT pathway, promoting leukemia progression." (PMID 40121502, 2025). "We also found that MMP14 is highly expressed in AML-MSCs, playing a crucial role in leukemia cell proliferation, apoptosis, and chemoresistance." (PMID 40121502, 2025). "MSC-derived MMP14 may promote AML progression and increase drug resistance through the secretion of PGE2, which activates the JAK-STAT pathway in leukemia cells." (PMID 40121502, 2025). "To elucidate why AML-MSCs support leukemia cell growth, we performed transcriptomic and proteomic analyses, along with joint OHSU-AML datasets prognostic analysis, which preliminarily confirmed that MMP14 plays a key role in AML development and progression." (PMID 40121502, 2025). "Mechanistically, the supportive effect of MSC-derived MMP14 on AML may operate through the secretion of PGE2, which activates the JAK-STAT pathway in leukemia cells." (PMID 40121502, 2025). "Knockdown of MMP14 in MSCs resulted in a decrease in the expression of P-STAT3 and P-STAT5 in leukemia cells, with no decrease in the expression of total STAT3 and STAT5." (PMID 40121502, 2025).
lung adenocarcinoma (4 papers, 2014 to 2025). A carcinoma that arises from the lung and is characterized by the presence of malignant glandular epithelial cells. "Both MMP14 mRNA and protein levels were significantly overexpressed in lung adenocarcinoma (LUAD) cells relative to normal tissue." (PMID 37752518, 2023). "A Western blot analysis showed the increased expression of MMP-14 in comparison to the expression in lung adenocarcinoma cells (A549)." (PMID 24489925, 2014). "Furthermore, Matrix metalloproteinase 14 (MMP14), a target gene of miR-1287-5p, promotes the proliferation, invasion, and migration of Lung adenocarcinoma (LUAD) cells." (PMID 37752518, 2023).
medulloblastoma (4 papers, 2009 to 2020). A malignant, invasive embryonal neoplasm arising from the cerebellum. "Immunohistochemical studies have revealed that the presence of VM is associated with the expression of MMP-2, MMP-14, EphA2 and laminin 5γ2 in medulloblastoma." (PMID 25202424, 2014). "While the low MT-MMP expression levels in ependymomas and medulloblastomas correlated well with their low infiltration tendency, we observed the overall maximum expression of MMP14, -15, -16, and -17 in pilocytic astrocytoma." (PMID 32872536, 2020). "When it comes to medulloblastomas, the literature is more limited; however, a study indicated that VM was present in about 22% of the examined medulloblastoma tissues and was associated with higher expression of matrix metalloproteinases (MMP-2, MMP-14), ephrin (Eph) A2, and laminin 5γ2." (PMID 33036204, 2020).
myeloma (4 papers, 2018 to 2023). "This review focuses on the role of MMP-1, MMP-2, MMP-7, MMP-9, MMP-13, MMP-14, and MMP-15 and the four types of TIMPs in the invasion of myeloma cells, angiogenesis, osteolytic osteopathy, to offer some novel perspectives on the clinical diagnostics and therapeutics of MM." (PMID 37823051, 2023). "Thus, osteoclasts not only support myeloma cell growth, but they also impede immune responses through several highly expressed negative regulators of immune response including, but not limited to, MMP9, MMP14, B7-H3, PD-L1, and PD-L2." (PMID 34150958, 2021).
nephrosclerosis (4 papers, 2020 to 2022). Hardening of the kidney due to infiltration by fibrous connective tissue (fibrosis), usually caused by renovascular diseases or chronic hypertension. "Vasko and colleagues confirmed that restoration of MMP-14 expression in SIRT1-depleted mice improved the angiogenic and matrilytic functions of the endothelium, prevented renal dysfunction, and attenuated nephrosclerosis." (PMID 32802201, 2020). "The following potential proteases for the different CKD aetiologies were identified: ADPKD (MMP7), MCD (CTSB, CTSD, CTSE, MEP1A, MMP7, PGA3), MGN (MMP3, MMP7, MMP9, MMP13, MMP14), IgAN (MMP7), FSGS (MMP3, MMP7), vasculitis (PGA3), nephritis (MMP7, MMP9), nephrosclerosis (MMP7), and DKD (MMP9)." (PMID 32427855, 2020).
pituitary adenomas (4 papers, 2019 to 2022). "ADAM12 and MMP14 are significantly correlated with cavernous sinus invasion in patients with pituitary adenomas." (PMID 34604068, 2021). "While MMP14 and ADAM10 regulate cell migration and invasion in pituitary adenomas, no clear function for SPOCK1 has been described so far in pituitary tissue." (PMID 35370944, 2022).
skin cancer (4 papers, 2001 to 2026). "MMP7, MMP11, and MMP14 play key roles in skin cancer progression." (PMID 40604111, 2025).
tendinopathy (4 papers, 2011 to 2024). "In regard to the expression of metalloprotease-encoding genes, increased expression of MMP2, MMP14, MMP16, ADAMTS2, ADAMTS3 as well as downregulation of MMP10 has also been found in tendinopathy." (PMID 38001919, 2023).
acute myeloid leukemia (3 papers, 2012 to 2025). Acute myeloid leukemia (AML) is a group of neoplasms arising from precursor cells committed to the myeloid cell-line differentiation. "Although MMP14 plays an important role in inflammation and cancer, the regulation and role of MSC-derived MMP14 in acute myeloid leukemia (AML) are largely unknown." (PMID 40121502, 2025).
ameloblastoma (3 papers, 2022 to 2025). The most common odontogenic tumor, arising from the epithelial component of the embryonic tooth and usually affecting the molar-ramus region of the mandible or maxilla. "Several studies also demonstrated that MMPs like MMP-1, MMP-2, MMP-7, MMP-9 and MMP-14 are involved in ECM degradation in the invasion of ameloblastoma [16,21,22,]." (PMID 35243014, 2022). "In addition, our microarray study suggested that MMP-14 showed moderately increased expression in the AM-3 ameloblastoma cells stimulated by MC3T3-E1 CM compared with the AM-3 ameloblastoma cells alone." (PMID 35243014, 2022). "In addition, microarray study showed that MMP-14 (MT1-MMP) showed moderately increased expression (2.297-fold) in the AM-3 ameloblastoma cells treated with MC3T3-E1 CM compared to the AM-3 ameloblastoma cells alone." (PMID 35243014, 2022).
bladder tumour (3 papers, 2004 to 2020). "In addition, these results suggested that cancerous cells of the low-grade urinary bladder tumor might silence the activity of MMP-14." (PMID 32049862, 2020).
dental caries (3 papers, 2017 to 2022). The decay of a tooth, in which it becomes softened, discolored, and/or porous. "Investigating the genetic association of MMP-10, MMP-14, and MMP-16 with dental caries shows that MMP-16 SNP rs2046315 is associated with dental caries." (PMID 36012195, 2022). "We investigated 28 SNPS in or near three MMP genes (MMP10, MMP14, and MMP16) for evidence of association with dental caries experience in 13 race- and age-stratified samples from 6 independent studies (n = 3600)." (PMID 28348596, 2017). "Here we investigated 28 genetic variants spanning the MMP10, MMP14, and MMP16 genes to detect association with dental caries experience in 13 age- and race-stratified (n = 3,587) samples from 6 parent studies." (PMID 28348596, 2017).
diabetic retinopathy (3 papers, 2020 to 2025). "Due to the higher levels of MMP-9 and MMP-14 in the pathogenesis of diabetic retinopathy, these proteins may probably be among the therapeutic targets in the prevention and treatment of retinopathy." (PMID 35729613, 2022). "Inhibition of the MMP-9 and MMP-14 proteins may be an alternative for suppressing diabetic retinopathy." (PMID 35729613, 2022). "Thus, treatments targeting the inhibition of MMP-9 and MMP-14 can be used in the treatment of diabetic retinopathy." (PMID 35729613, 2022). "Thus, MMP-9 and MMP-14 protein levels can be used for the diagnosis and treatment in diabetic retinopathy." (PMID 35729613, 2022). "Diabetic retinopathy can be suppressed by inhibition of MMP-9 and MMP-14 levels which indicates a new form of treatment." (PMID 35729613, 2022). "Thus, we aimed to compare MMP-9 and MMP-14 levels in diabetic and non-diabetic patients which could be the biomarkers of diabetic retinopathy." (PMID 35729613, 2022).
fibrosis (3 papers, 2016 to 2020). the formation of excess fibrous connective tissue in an organ or tissue in a reparative or reactive process. "Hence, we examined the expression pattern of MMP-14 in the fibrotic liver by performing mass cytometry (cyTOF) analysis at the peak of CCl4-induced fibrosis (48 h)." (PMID 32296422, 2020). "Further characterization of the mechanism of action of MMP14 in DD may lead to the validation of this protein as a therapeutic target in fibrosis." (PMID 28886342, 2017).
glomerulosclerosis (3 papers, 2017 to 2024). A hardening of the kidney glomerulus caused by scarring of the blood vessels. "As molecular drivers of glomerulosclerosis in diabetic UNx and UNx-Renin mice, our glomerular gene expression analysis confirmed the upregulation of several fibrogenesis-associated genes (e.g. Col1a1, Col5a1, Col5a3, Fn1 and Mmp14)." (PMID 34494644, 2021). "In DN, MMP14 expression levels are elevated, and it participates in pathological processes such as glomerulosclerosis and accumulation of the extracellular matrix." (PMID 38292407, 2024). "Col5a3, Fn1 and Mmp14 were upregulated in the kidney cortex and glomeruli of UNx-Renin mice compared to both db/m controls and UNx mice, underscoring the advanced progression of glomerulosclerosis in this model of late-stage DKD." (PMID 34494644, 2021).
head and neck cancer (3 papers, 2021 to 2024). A primary or metastatic malignant neoplasm affecting the head and neck. "Assessment of regional lymph nodes from head and neck cancer patients confirmed the presence of MMP14 and Fc receptors in SSMs." (PMID 34168645, 2021).
Hydrocephalus (3 papers, 2023 to 2025). Hydrocephalus is an active distension of the ventricular system of the brain resulting from inadequate passage of CSF from its point of production within the cerebral ventricles to its point of absorption into the systemic circulation. "Mmp14 KO mice do however have defective ependymal motile cilia, which are thought to underlie hydrocephalus in these mice." (PMID 37169079, 2023).
ischemic stroke (3 papers, 2011 to 2024). A stroke disorder caused by obstruction of blood flow to the brain, due to thrombotic (local blood clot formation) or embolic (due to a blood clot or other material traveling from another site) event. "pGSN is cleaved in vitro by MMP-3, MMP-2, MMP-1, MMP-14 and MMP-9 which may be the cause of the severe depletion of pGSN observed in patients who suffer ischemic stroke." (PMID 22047744, 2011).
keloid (3 papers, 2007 to 2025). An irregularly shaped, elevated mark on the skin caused by deposits of excessive amounts of collagen during wound healing. "The results of the FOXP1-Cut&Tag experiment in keloid fibroblasts revealed that FOXP1 is associated with the SEs of SERPINH1, MMP14, COL5A1, COL16A1, and SPARC, all of which exhibited significant signal enrichment in their SE regions." (PMID 40702440, 2025). "This is based on previous studies showing that DDR2 drives collagen-induced MMP14 activation in fibroblasts and that enhanced MMP14 activity in keloid fibroblasts is responsible for continued collagen deposition and keloid progression." (PMID 41259339, 2025). "A number of MMPs were equally expressed in leiomyomas, keloids and peritoneal adhesions with the exception of lower MMP-14, MMP-24 and MMP-28 expression in leiomyomas, suggesting that these tissues are potential target of their proteolytic actions." (PMID 17718906, 2007).
myopia (3 papers, 2016 to 2025). "The reported changes include transforming growth factors (TGF-β 1–3) and MMPs (MMP-2 and MMP-14) suggesting that growth factors and MMPs are critical components in scleral remodeling pathways during myopia development." (PMID 27870875, 2016).
Osteopenia (3 papers, 2013 to 2019). Osteopenia is a term to define bone density that is not normal but also not as low as osteoporosis. "Previous studies reported a phenotype for MT1-MMP (membrane type 1- matrix metalloproteinase, also known as MMP14)-deficient mice that was remarkably similar to that of the Zdhhc13 mutant, namely, impaired endochondral ossification, defective angiogenesis, and osteopenia." (PMID 24637783, 2014).
pancreatic adenocarcinoma (3 papers, 2017 to 2021). "CLDN7 palmitoylation can promote cell invasion by association with uPAR, MMP14 and CD147, and also play a role in epithelial-mesenchymal transition (EMT) of pancreatic adenocarcinoma cells." (PMID 28055967, 2017).
renal fibrosis (3 papers, 2020 to 2023). A final common manifestation of a wide variety of chronic kidney diseases characterized by glomerulosclerosis and tubulointerstitial fibrosis. "SIRT1 has also been shown to play a role in renal fibrosis via the downregulation of matrix metalloproteinase-14 (MMP14)." (PMID 37371668, 2023). "IMN is often accompanied by renal fibrosis, and we found that the expression of MMP-14 increased significantly in IMN, but no obvious changes were found in MMP-2 and MMP-9." (PMID 34819020, 2021).
serous ovarian carcinoma (3 papers, 2021 to 2025). "Even though the TCGA datasets from three studies on 1680 serous ovarian carcinomas suggests a prognostic utility (OS and PFS) of MMP-14 based on its altered and unaltered genetic expression in serous ovarian cancer patients, no such links could be made with TIMP-1, -3 or MMP-2, -9, and -11." (PMID 35047406, 2021).
Winchester syndrome (3 papers, 2018 to 2025). "Homozygous mutations in the SH3PXD2B and MMP14 genes cause Frank-Ter Haar syndrome and Winchester syndrome, respectively, whereas MMP2 gene mutation causes Torg and MONA syndromes." (PMID 41246610, 2025). "Loss of either MMP2 or MMP14 results in a spectrum of recessive skeletal dysplasias with osteolysis, encompassing multicentric osteolysis, nodulosis and arthropathy (MONA, MIM #259600) and Winchester syndrome (WS, MIM #277950)." (PMID 29741626, 2018).
AIDS (2 papers, 2010 to 2018). A syndrome resulting from the acquired deficiency of cellular immunity caused by the human immunodeficiency virus (HIV). "Sections from ten AIDS-associated KS patients were double-stained for PROX1 and MMP14." (PMID 29934628, 2018).
aortic aneurysm (2 papers, 2016 to 2020). A ruptured aneurysm located in the wall of the proximal portion of the descending aorta proceeding from the arch of the aorta. "TIMP2 inhibits the activity of MMP2, but it is also participatory in indirect activation of MMP2 through association with MMP14 that may promote cancer progression and, more importantly in the context of DSLD, aortic aneurysm development." (PMID 33028365, 2020).
aortic stenosis (2 papers, 2017 to 2025). Aortic valve stenosis is a aortic valve disease caused by the incomplete opening of the aortic valve. "For example, MMP-2 and MMP-14 levels robustly increase in LV pressure overload models and myocardial biopsies of aortic stenosis (AS), whereas the levels of MMP-14, MMP-7, MMP-8, and MMP-9 increase in end-stage dilated cardiomyopathy." (PMID 28484397, 2017).
arthropathy (2 papers, 2019 to 2024). Any disorder of the joints. "Among the MT-MMPs, MMP-14 (MT1-MMP) plays predominant role in joint disorders." (PMID 30949048, 2019). "Specifically, homozygous inactivating mutations of the matrix metalloproteinase 2 (MMP2), MMP14, or SH3PXD2B genes may cause defective collagen remodeling and result in the allelic variants of MONA (multicentric osteolysis, nodulosis and arthropathy), Torg or Winchester syndrome." (PMID 38681749, 2024).
ascending aortic aneurysm (2 papers, 2019 to 2025). "Our study aimed to analyze MMP-2 isoforms as well as the MMP-2 activating enzymes TIMP-2 and MMP-14 in ascending aortic aneurysm and control tissue from patients undergoing CABG." (PMID 30794673, 2019).
B-cell lymphoma (2 papers, 2013 to 2020). "Distal cis-regulatory elements of MMP14 are frequently deleted in B-cell lymphoma, leading to MMP14 downregulation." (PMID 33117405, 2020).
cardiac hypertrophy (2 papers, 2020 to 2023). "Now, many TNF-dependent genes linked to ECM remodeling as well as AF are upregulated with exercise in WT atria compared to sedentary, including Mmp14, Fgf2 (i.e., fibroblast growth factor 2, which activates p38 and induces cardiac hypertrophy as well as fibrosis), Gsk3β, and Tln1." (PMID 33424629, 2020).
cardiac ischemia (2 papers, 2020 to 2023). "Eight genes (Aif1, Apoe, Arg1, Col1a1, Gpx7, Hmox1, Mmp14, and Sirpa) were significantly differentially expressed in the rat myocardial ischemia-reperfusion model." (PMID 36826575, 2023).
Cirrhosis (2 papers, 2014 to 2023). A chronic disorder of the liver in which liver tissue becomes scarred and is partially replaced by regenerative nodules and fibrotic tissue resulting in loss of liver function. "QuantSeq 3′ mRNA sequencing revealed thirty-three downregulated genes associated with ECM after the NK cell treatment of CCl4-induced cirrhosis, including six MMP genes (MMP3, MMP8, MMP9, MMP11, MMP12, and MMP14)." (PMID 37189708, 2023). "In established end-stage injury with cirrhosis there is increased expression of MMP-2, MMP-9, MMP-14 as well as TIMP-1 and TIMP-2." (PMID 25076423, 2014).